CD14 (CD14 molecule)
Diseases named in the same sentence as CD14 in open-access papers (continued):
Sharing a sentence is not in itself a finding about the gene and the disease.
lipid metabolism disorders (1 paper, 2016). "In addition to a large number of expected disease-tissue associations (e.g., tauopathies and brain tissues), we also find a number of less obvious disease-tissue associations, such as macular degeneration and liver, or lipid metabolism disorders and CD14 monocytes." (PMID 27748412, 2016).
lupus erythematosus (1 paper, 2019). An autoimmune, connective tissue chronic inflammatory disorder affecting the skin, joints, kidneys, lungs, heart, and the peripheral blood cells. "In the same line, the rs4810485 SNP was associated with CD40 protein expression on CD14+ monocytes and CD19+ B cells from lupus erythematosus patients assessed by flow cytometry." (PMID 31183392, 2019).
lupus-like syndrome (1 paper, 2013). "Repeated injections of low-dose LPS (ligand of TLR4/CD14) to female MRL/n, BXSB, or NZW mice accelerates the development of lupus-like syndrome, increasing the production of autoantibodies and worsening the renal function impairment." (PMID 24252506, 2013).
lymph node tumor (1 paper, 2019). "Myeloid-derived suppressor cells were predominantly stained by CD14 and were numerous at the bulky and lymph node tumor sites, but were less intense in adenocarcinoma." (PMID 30696472, 2019).
lymphoid leukaemia (1 paper, 2024). "CD33 on CD14+ monocyte mediated the causal relationship between DHEAS (Mediated proportion = -9.72%[-17.8%,-1.65%]), Androstenediol (3beta,17beta) disulfate (Mediated proportion = -14.6% [-26.9%,-2.27%]), and lymphoid leukaemia." (PMID 39351228, 2024).
malignant glioma (1 paper, 2014). A grade III or grade IV glioma arising from the central nervous system. "In a clinical trial of patients with malignant gliomas who were treated with aflibercept, a decrease in VEGFR1+CD14+ monocytes from baseline to 24 hours was associated with better response." (PMID 24809734, 2014).
measles (1 paper, 2014). A highly contagious viral infection caused by the measles virus. "We exposed the CD14 depleted PBMCs from the same donors which were used for DC generation to measles vaccine and harvested T-cell 5 days later." (PMID 24616721, 2014).
meningococcal disease (1 paper, 2009). "In surviving meningococcal disease patients DNA analysis of CD14 C-159T and TLR 4 Asp299Gly polymorphisms was performed, as they are part of the innate immune response to bacterial determinants." (PMID 19809507, 2009). "Genotype distribution of the CD14 C-159T and TLR4 Asp299Gly variants among patients with meningococcal disease compared to controls." (PMID 19809507, 2009). "We could not observe a significant influence of CD14 C-159T and TLR4 Asp299Gly polymorphisms on the risk of developing IMD in surviving meningococcal disease patients." (PMID 19809507, 2009).
microcephaly (1 paper, 2019). A congenital or acquired developmental disorder in which the circumference of the head is smaller than normal for the person's age and sex. "Brain slices of a ZIKV-positive human fetus (5 months) diagnosed with microcephaly were stained for the viral protein NS1 together with the leukocyte marker CD45, the monocytic marker CD14, or the myeloid markers CD68 or CD163." (PMID 31562326, 2019).
morbid obesity (1 paper, 2023). An excess of body weight, normally defined as an individual with a body mass index greater than 35 or a body weight greater than one hundred percent of ideal body weight. "B cells (CD19+) and monocytes (HLA-DR+, CD14+, CD16var) tend to be increased in patients with morbid obesity." (PMID 37266430, 2023). "Taking peripheral blood immune cell compartments into account, the patients with morbid obesity demonstrated a considerable increase of a Lin-, HLA-DR-, CD14+ sub-population, which phenotypically represents monocytic Myeloid derived suppressor cells (mo-MDSCs)." (PMID 37266430, 2023). "Furthermore, we found an increased population of monocytic CD14+, HLA-DR-, CD11b+, CXCR3+ cells in patients with morbid obesity and an overall reduction of the HLA-DR monocytic expression compared to the control population." (PMID 37266430, 2023). "Apart from that, we described highly affected, distinct immune cell subsets, defined as CD127+ memory T cells and monocytic CD14+, HLA-DR, CD11b+, CXCR3+ cells, that might play a significant role in understanding and further decoding the etiopathogenesis of morbid obesity." (PMID 37266430, 2023).
mucinous tumours (1 paper, 2025). "In addition, regardless of MMR status, mucinous tumours displayed higher densities of CD14+HLADR– immature monocytic cells." (PMID 39966658, 2025).
mycoplasmosis (1 paper, 2017). "Similarly, the median proportion of PD‐L1+CD11b+CD14+ cells was higher in cattle with mycoplasmosis than in control cattle (P < 0.05)." (PMID 28544524, 2017). "In the present study, PD‐L1 expression on CD14+CD11b+ monocytes and PD‐1 expression on CD4+ T cells was found to be upregulated in bovine mycoplasmosis." (PMID 28544524, 2017).
myelofibrosis (1 paper, 2019). A partial or complete replacement of the bone marrow stroma by fibrous tissue. "Taken together, our data suggest that PMF monocytes induce myelofibrosis-like phenotype in immunodeficient mice and that PMF and normal BM-derived CD14+/CD34- monocytes give rise to megakaryocyte progenitor cells." (PMID 31569199, 2019).
ocular sarcoidosis (1 paper, 2014). A leading cause of inflammatory eye disease is sarcoidosis. "Intriguingly, the frequency of IL-17RC+ cells among CD3+CD4+ helper T cells, CD14+ monocytes, CD19+ B cells, and CD56+ NK cells was similar between healthy controls and ocular sarcoidosis patients." (PMID 24885153, 2014).
osteitis (1 paper, 2022). "In line with this, staining for markers on immune cells, such as CD14 and CD68, were increased in the infected groups compared to their non-infected counterparts, indicating ongoing osteitis and systemic responses of the immune system." (PMID 35268930, 2022).
osteomyelitis (1 paper, 2014). An acute or chronic inflammation of the bone and its structures due to infection with pyogenic bacteria. "In a series of in vitro studies, we were now able to show that CCL3 induced the differentiation of CD14+ monocytes to osteoclasts, which might be relevant for bone degradation in osteomyelitis, because peripheral blood monocytes are known to be osteoclast precursors." (PMID 24795505, 2014).
otitis media (1 paper, 2014). Inflammation of the anatomical structures of the middle ear, which is most often caused by an infectious process. "Previous candidate gene studies associated a number of immune system genes with otitis media, which included TNF-α, IL-6, IL-10, Tlr4, surfactant, CD14, FcγRIIa, IFNγ, Eya4, p73, MyD88, Fas, E2f4, Plg, Fbxo11, and Evi1." (PMID 24466073, 2014).
Pancytopenia (1 paper, 2019). An abnormal reduction in numbers of all blood cell types (red blood cells, white blood cells, and platelets). "In contrast, the relative levels (i.e. percentage among total CD14+ monocytes) varied during pancytopenia when tested 6–8 days after stem cell reinfusion." (PMID 31703617, 2019).
pediatric cancer (1 paper, 2015). "High expression of FOXP3, CD14, and ARG1 mRNA in the primary tumors of high-risk NB patients was predictive of better survival, suggesting that the immune status of the tumor may influence the natural history of this pediatric cancer." (PMID 26161395, 2015).
Peptic ulcer (1 paper, 2023). The term peptic ulcer refers to acid peptic injury of the digestive tract, resulting in mucosal break reaching the submucosa. "Related studies have found that CD163 and CD14 are increased in H. pylori infection, especially in patients with peptic ulcers." (PMID 36973348, 2023).
peripheral artery occlusive disease (1 paper, 2017). "Similar to that observed in patients with CAD, CD14++CD16+ monocyte levels increased in patients with peripheral artery occlusive disease." (PMID 28789689, 2017).
Pneumocystis infection (1 paper, 2010). "Among the genes that were affected by dexamethasone and further affected by Pneumocystis infection, Mgst1 and Hspa1b genes were down-regulated, while Cd14, Irf8, Il1b, Cxcl13, Cxcr4, Fn1, Irf1, Cd74, S100a9, and Spp1 genes were up-regulated in all four groups." (PMID 20377877, 2010).
polyarticular JIA (1 paper, 2024). "Another noteworthy observation related to monocytes is the enhanced expression of CD14 on the surface of CD14++/CD16- monocytes in systemic JIA and polyarticular JIA." (PMID 38459548, 2024).
prediabetes (1 paper, 2026). "The CD14+/KDR+ expression in MOMCs incubated with HDL from T2D patients was lower than that observed in prediabetes and normoglycemic individuals (46% vs. 52% and 61%, respectively; p = 0.002)." (PMID 41893343, 2026).
pregnancy disorder (1 paper, 2020). A disorder that is related to pregnancy. "To date, there has been a lack of knowledge regarding whether TLR4 accessories such as CD14 and MD-2 are important in pregnancy and whether these accessory molecules could be promising drug targets for combinatorial treatment of various pregnancy disorders." (PMID 32508811, 2020).
purpura (1 paper, 2022). A small blood vessel hemorrhage into the skin and/or mucous membranes. "Already, the nonlesional skin revealed marked immunostaining of complement factor I, iC3b, CD11b, and CD14, and their expression increased sequentially in initial petechial and palpable purpura lesions." (PMID 35747245, 2022). "In this study, frozen skin biopsies from the nonlesional skin, initial petechial lesion, and palpable purpura lesion from 10 patients with immunocomplex-mediated small vessel vasculitis were studied immunohistochemically for complement factor I, iC3b, CD11b, and CD14." (PMID 35747245, 2022).
pustular psoriasis (1 paper, 2020). "In a previous report, in a set of five patients with pustular psoriasis, depletion of CD14+CD16+ circulating monocytes ameliorated symptoms and, interestingly, no change in TNF was observed, what suggests that other factors produced by monocytes may play a role in the pathogenesis of the disease." (PMID 32269570, 2020).
pyrexia (1 paper, 2020). "Experimental infection with ORF1 and ORF71 deletion mutants revealed a brief period of pyrexia, low virus shedding, and decreased cytokine response (IFNα, IL-10, and soluble CD14); however, they had comparable viremia to Ab4-wt." (PMID 32911663, 2020).
Q fever (1 paper, 2019). A bacterial infection caused by Coxiella burnetii. "Conversely, we found that the E-cad protein expression at the surface of the cells of patients with Q fever was significantly increased on both CD14+ and CD16+ monocytes from persistent Q fever patients." (PMID 31293984, 2019). "Moreover, in contrast to the data obtained with cell subpopulations of acute Q fever patients, high cell surface expression of E-cad was found in both CD14+ and CD16+ cell subpopulations from persistent Q fever patients." (PMID 31293984, 2019).
Rectal prolapse (1 paper, 2018). Protrusion of the rectal mucous membrane through the anus. "One naïve CD14-/- mouse was euthanized and removed from the study due to a rectal prolapse." (PMID 30485272, 2018).
Respiratory tract infection (1 paper, 2022). An infection of the upper or lower respiratory tract. "Our data suggest a beneficial role for CD14 in RSV immune signaling, and we extend these findings to a clinical phenotype for CD14 deficiency associated with recurrent respiratory tract infections." (PMID 35429403, 2022).
rosacea (1 paper, 2025). A chronic erythematous skin disorder that affects the face. "Our study revealed HLA DR on CD14− CD16+ monocyte is a risk factor for the incidence of rosacea." (PMID 41431076, 2025). "TR B cell %lymphocyte, CD25 on IgD− CD24− B cell, and HLA DR on CD14− CD16+ monocyte are risk factors for the onset of rosacea, while central memory CD4− CD8− T cell AC, CCR7 on naive CD4+ T cell, CD14+ CD16− monocyte AC, and CD62L − mDC are protective factors for the onset of rosacea." (PMID 41431076, 2025). "Among them, transitional (TR) B cell %lymphocyte (odds ratio [OR] = 1.170, 95% confidence interval [CI] = 1.001–1.368), CD25 on IgD− CD24− B cell (OR = 1.151, 95% CI = 1.013–1.307), and HLA DR on CD14− CD16+ monocyte (OR = 1.136, 95% CI = 1.007–1.281) increased risk of rosacea." (PMID 41431076, 2025).
Rotavirus infection (1 paper, 2024). Infection with any of the rotaviruses. "In newborn piglets, rotavirus infection can reduce the total number of CD14 cells and monocytes in the intestinal lymph nodes, and also decrease the macrophage population in the mesenteric lymph nodes and ileal Peyer’s nodes." (PMID 38698473, 2024). "In summary, rotavirus infection can reduce the number and activity of CD14 cells, monocytes and macrophages in host, and stimulate the expression of pro-inflammatory factors/chemokines secreted by these cells, thereby causing a decrease in immune function, and inducing inflammation." (PMID 38698473, 2024).
scoliosis (1 paper, 2025). A congenital or acquired spinal deformity characterized by lateral curvature of the spine. "In our study, we observed that HLA DR on CD14+ CD16+ monocyte was associated with a reduced risk of scoliosis, and SNHG14, SNORA33, and NET1 shared the same variant with HLA DR on CD14+ CD16+ monocyte." (PMID 40177401, 2025). "SNHG14, SNORA33, NET1, and SNORD100 shared the same variant with HLA DR on CD14+ CD16+ monocyte which could decrease the risk of scoliosis." (PMID 40177401, 2025). "Terminally differentiated CD8+ T cell %CD8+ T cell (p-value, 0.006; OR, 0.736; 95%CI, 0.591−0.916), CD25++ CD8+ T cell absolute count (p-value, 0.043; OR, 0.836; 95%CI, 0.702−0.995), and HLA DR on CD14+ CD16+ (p-value, 0.006; OR, 0.868; 95%CI, 0.783−0.961) decrease the risk of scoliosis." (PMID 40177401, 2025).
scrub typhus (1 paper, 2013). Scrub typhus is a rare dust mite-borne infectious disease caused by the Orientia tsutsugamushi bacterium and characterized clinically by an eruptive fever which is potentially serious. "Recently, a paper reported that O. tsutsugamushi mainly infects “inflammatory” CD14/LSP-1/CD68 positive monocytes and CD1a/DCSIGN/S100/FXIIIa and CD163 positive dendritic cells in stained eschar skin biopsies from scrub typhus patients." (PMID 23301113, 2013).
Senile plaques (1 paper, 2024). Senile plaques are extracellular deposits of amyloid in the gray matter of the brain. "Additionally, other studies have demonstrated the increased expression of TLR2, TLR4, TLR5, TLR7, TLR9, and the co-receptor CD14 in microglial cells surrounding senile plaques in the brain tissues of patients with AD and AD mouse models." (PMID 38360834, 2024).
spinal tuberculosis (1 paper, 2018). "In the present study, we identified the roles of MBL2, CD14 and TNF-α gene polymorphisms in the susceptibility to spinal tuberculosis in a Chinese population." (PMID 29298876, 2018).
spirochete infection (1 paper, 2022). "Our results also confirm that the CD14+ macrophages have a particularly important role in clearance of B. burgdorferi and the immunologic response to spirochete infection." (PMID 36232290, 2022).
Splenomegaly (1 paper, 2019). Abnormal increased size of the spleen. "PMF BM-derived CD14+/CD34- monocytes engrafted and induced a PMF-like phenotype with splenomegaly, myeloid hyperplasia with clusters of atypical megakaryocytes, persistence of the JAK2V617F mutation, and BM and spleen fibrosis." (PMID 31569199, 2019).
synovitis (1 paper, 2025). Inflammation of a synovial membrane. "High-grade synovitis is associated with greater PRG4-CD44 signaling dysfunction and inhibition of XO prevents pro-inflammatory activation of CD14 + cells isolated from patients with high-grade synovitis." (PMID 41282165, 2025). "The efficacy of febuxostat was more pronounced in CD14 + cells isolated from high-grade synovitis, and this correlated with the stronger XO staining observed in these specimens." (PMID 41282165, 2025).
T-cell lymphoma (1 paper, 2022). "To further explore that possibility, we generated human monocyte-derived macrophages, using CD14+ monocytes, obtained from HDs, cultured with CFCM obtained from human mature T-cell lymphoma (MTCL) cell lines and primary specimens." (PMID 36970721, 2022).
tendinopathy (1 paper, 2019). "To verify the effect of aspirin on tendinopathy, we observed the number of changes in iNOS+M1 Mφs, CD14+ monocytes and CD206+ M2 Mφs." (PMID 31225686, 2019).
thymic tumors (1 paper, 2026). "For instance, in thymic tumors, oncomatrix remodeling may enhance the infiltration of CD14+ CD16+ monocytes, exacerbating immune evasion and tumor progression while impairing protective cells like NK cells through metabolic suppression." (PMID 41497137, 2026).
thymoma (1 paper, 2026). A neoplasm arising from the epithelial cells of the thymus. "Thus, CCR2 on CD14+ CD16+ monocytes emerges as a critical driver of the transition from benign to malignant thymomas." (PMID 41497137, 2026). "Our study revealed that the expression of CCR2 on CD14+ CD16+ monocytes promotes both benign and malignant thymomas." (PMID 41497137, 2026).
thyroid disease (1 paper, 2024). "CD14 may contribute to the recognition and presentation of self-antigens in GD, promoting the activation of immune responses against the thyroid tissue, but the specific involvement of CD14 in thyroid disease is still an area of ongoing research." (PMID 39351300, 2024).
tongue cancer (1 paper, 2022). A malignant neoplasm affecting the tongue. "A tongue cancer study indicated that malignant transformation was accompanied by an increase in CD4+ and B cells, in addition to CD8+ and CD14+ cells." (PMID 36009387, 2022).
transient ischemic attack (1 paper, 2025). A brief attack (from a few minutes to an hour) of cerebral dysfunction of vascular origin, with no persistent neurological deficit. "Beyond local injury, Cd14 + extracellular vesicles from activated monocytes/microglia propagate systemic inflammation, correlating with transient ischemic attack (TIA) diagnosis and cardiovascular risk." (PMID 41354822, 2025).
Type 2 diabetic nephropathy (1 paper, 2021). "Type 2 diabetic nephropathy patients have pro-inflammatory CD14+ and CD16+ monocyte disorder." (PMID 34735495, 2021).
ulcers (1 paper, 2021). "In addition, it can also reduce the expression of CD14 and IL-6 in colonic mucosa and alleviate the severity of ulcers." (PMID 34692749, 2021).
uveal melanoma (1 paper, 2020). A melanoma derived from melanocytes of the uveal tract. "Uveal melanoma patients harbored a higher fraction of cells with an M-MDSC phenotype (CD14+HLA-DR−/low)." (PMID 33344043, 2020).
viral pneumonia (1 paper, 2025). Inflammation of the lung parenchyma that is caused by a viral infection. "This analysis identified Sting, Ptpn6, Prkcd, and Cd14 as key genes involved in viral pneumonia." (PMID 40666504, 2025).
vulvar intraepithelial neoplasia (1 paper, 2020). Intraepithelial neoplasia of the vulvar squamous epithelium. "VSCC is also characterized by a high infiltrate of CD14+ M1 macrophages, which become the dominant population, and the presence of CD14+ cells represents an independent negative prognostic factor for recurrence-free survival (RFS) in HPV-related vulvar intraepithelial neoplasia." (PMID 33375467, 2020).